FXN (frataxin)
Diseases named in the same sentence as FXN in open-access papers (continued):
Sharing a sentence is not in itself a finding about the gene and the disease.
Charcot-Marie-Tooth disease type 1A (1 paper, 2019). Charcot-Marie-Tooth disease type 1A (CMT1A) is a type ofinherited neurological disorder that affects the peripheral nerves. "Muscle biopsy and genetic testing regarding Charcot-Marie-Tooth disease type 1A (CMT1A), Friedrichs ataxia (trinucleotide repeat in FXN), Loeys-Dietz syndrome (TGFBR1, TGFBR2) and Ehler Danlos syndrome type IV (COL3A1) were all normal as well as the karyotype of lymphocytes (46,XX)." (PMID 31053103, 2019).
colon adenocarcinoma (1 paper, 2013). "It has been shown that extra-mitochondrial localisation of frataxin and its association with ISCU1 play a key role in enterocyte-like differentiation of the human colon adenocarcinoma cell line Caco-2." (PMID 23658834, 2013).
Duchenne muscular dystrophy (1 paper, 2024). Duchenne muscular dystrophy (DMD) is a neuromuscular disease characterized by rapidly progressive muscle weakness and wasting due to degeneration of skeletal, smooth and cardiac muscle. "These are Duchenne muscular dystrophy (DMD), a muscular dystrophy altering dystrophin expression, Friedrich's ataxia (FA), a rare neuromuscular condition reducing frataxin expression, and Pompe disease, a lysosomal storage disorder driven by acid α‐glucosidase deficiency." (PMID 38095849, 2024).
esophageal cancer (1 paper, 2023). A primary or metastatic malignant neoplasm involving the esophagus. "constructed a prognostic map for esophageal cancer, utilizing eight genes, including CDCA4, UBE2Z, AMTN, AK1, TLE1, FXN, ZBTB6, and APLN." (PMID 38098487, 2023).
Hypercalcemia (1 paper, 2025). An abnormally increased calcium concentration in the blood. "Failed to improve neurological function (SARA, 9-HPT, 8-MWT, PATA) but increased FXN levels in platelets at 5.5–7.0 pg./μg dose range. out of 20 participants discontinued due to mild hypercalcemia." (PMID 40342369, 2025).
Insulin resistance (1 paper, 2024). Increased resistance towards insulin, that is, diminished effectiveness of insulin in reducing blood glucose levels. "In this study, we confirmed that the FXN deficiency mouse model YG8R develops insulin resistance in elder individuals by disturbing lipid metabolic homeostasis in adipose tissues." (PMID 39191875, 2024). "We uncovered the interplay between FXN expression and lipolysis and found that impairment of lipolysis, particularly the white adipocytes, is an early event, likely, as a primary cause for insulin resistance in FRDA patients at later age." (PMID 39191875, 2024). "In conclusion, FXN deficiency impairs the lipolysis, far earlier than insulin resistance." (PMID 39191875, 2024).
kidney damage (1 paper, 2024). "It has not been previously reported that these mice experience kidney damage, or any FXN loss in the kidneys." (PMID 39363102, 2024).
left ventricular hypertrophy (1 paper, 2024). Enlargement of the LEFT VENTRICLE of the heart. "Loss of FXN in the heart causes dilated left ventricular hypertrophy, ultimately resulting in death due to HF in these mice." (PMID 39363102, 2024).
metabolic disease (1 paper, 2021). "These events are complex, seemingly involving many different mechanisms that eventually lead to a relatively selective neurological and systemic disease—a true metabolic disease from frataxin deficiency." (PMID 34046211, 2021).
multiple sclerosis (1 paper, 2019). A progressive autoimmune disorder affecting the central nervous system resulting in demyelination. "Lastly, DMF dosed Multiple Sclerosis (MS) patients showed significant increase in FXN expression by ~85%." (PMID 31158268, 2019).
Myoclonus (1 paper, 2015). Very brief, involuntary random muscular contractions occurring at rest, in response to sensory stimuli, or accompanying voluntary movements. "We have observed spinal segmental myoclonus (SSM) with unstable expansion of GAA repeats in frataxin gene." (PMID 26180750, 2015).
neuro-degenerative disease (1 paper, 2007). "Frataxin in its mutated form causes the neuro-degenerative disease Friedrich’s ataxia." (PMID 19455237, 2007).
Optic neuropathy (1 paper, 2021). "Decreased expression of frataxin could cause pathologic changes in restricted groups of tissues and it has been proposed that optic neuropathy in FRDA is a result of the increased sensitivity of RGC to oxidative stress." (PMID 34941648, 2021).
pancreatic cancer (1 paper, 2021). "Results revealed that low expression of FXN (frataxin) and high expression of MYC were associated with advanced grades of pancreatic tumors." (PMID 34711879, 2021). "We conducted a correlation analysis to investigate whether iron homeostasis genes, FXN and MYC, are also associated with ferritin in contributing pancreatic cancer progression." (PMID 34711879, 2021).
prostate carcinoma (1 paper, 2022). A carcinoma that arises from epithelial cells of the prostate gland. "Exposing prostate cancer cells to abiraterone and MDC3100 results in downregulation of mitochondrial proteins such as FXN (frataxin), ACO2 and TOMM20, mitochondrial swelling, mitochondrial depolarization and decreased mitochondrial DNA copy number." (PMID 35317831, 2022).
retinal ischemia (1 paper, 2018). A ischemic disease that involves the retina. "Retinal ischemia/reperfusion significantly reduced the thickness of the GCL/IPL by approximately 20% on average in MGCre-FXN mice compared with MGCre-B6 animals." (PMID 29555919, 2018). "The aim of this study was to evaluate the effect of frataxin overexpression in Müller cells on neuronal survival after retinal ischemia/reperfusion in the mouse in vivo." (PMID 29555919, 2018). "Together with the increased antioxidative response, these results indicate that FXN potentiates Müller cell-mediated neuroprotection after acute retinal ischemia/reperfusion by increasing the neurotrophic support." (PMID 29555919, 2018). "Retinal ischemia/reperfusion was induced in mice overexpressing frataxin in Müller cells by transient elevation of intraocular pressure." (PMID 29555919, 2018).
schizophrenia (1 paper, 2022). A major psychotic disorder characterized by abnormalities in the perception or expression of reality. "In two probands of these 14 families, we detected rare TREs in three genic regions (CALCOCO2 and FXN in one family, and SHANK1 in the other family) that were also identified in our primary schizophrenia cohort." (PMID 35546631, 2022).
spastic ataxia (1 paper, 2020). "We should to aware of a diagnosis of ARSACS in the patient who is presented with FXN gene negative early-onset spastic ataxia." (PMID 32775015, 2020). "At present, ARSACS is recognized as a rare, worldwide, inherited movement disorder in which we should to aware of a diagnosis of this disorder in the patient who is presented with FXN gene negative early-onset spastic ataxia." (PMID 32775015, 2020).
X-linked sideroblastic anaemia (1 paper, 2022). "Defects in genes associated with mitochondrial iron homeostasis, such as Frataxin and ABC7, cause secondary OXPHOS dysfunction and are related to FRDA and X-linked sideroblastic anaemia and ataxia (XLSA/A), respectively." (PMID 35466209, 2022).
neurodegenerative disease (69 papers, 2008 to 2025). A disorder of the central nervous system characterized by gradual and progressive loss of neural tissue and neurologic function. "Redox homeostasis is significantly altered in Friedreich’s Ataxia (FRDA; OMIM #229300), an inherited neurodegenerative disease caused by GAA repeat expansion within the first intron of the FXN gene coding for the mitochondrial protein frataxin (Fxn)." (PMID 40308559, 2025). "Friedreich’s ataxia (FA) is a neurodegenerative disease resulting from a mutation in the FXN gene, leading to mitochondrial frataxin deficiency." (PMID 37701569, 2023). "An HCM-like phenotype can be encountered in other conditions involving LVH, such as FA, which is a neurodegenerative disease caused by a GAA trinucleotide repeat expansion in frataxin gene (FXN)." (PMID 35269756, 2022). "In this review, we explore the paradigmatic example of frataxin, an iron binding protein involved in Fe–S cluster biogenesis, and whose impairment causes a neurodegenerative disease called Friedreich’s Ataxia (FRDA)." (PMID 35203634, 2022). "Friedreich’s ataxia (FRDA) is a neurodegenerative disease caused by decreased expression of frataxin, a protein involved in many cellular metabolic processes, including mitochondrial oxidative phosphorylation (OXPHOS)." (PMID 34652504, 2022). "FRDA is a rare neurodegenerative disease caused by a deficiency in the expression levels of frataxin, a small mitochondrial protein considered as an iron-binding protein." (PMID 33672495, 2021). "Frataxin is a highly conserved protein whose deficiency results in the neurodegenerative disease Friederich’s ataxia." (PMID 33348670, 2020). "It is a neurodegenerative disease produced by mutations in GAA triplet expansion in the first intron of the frataxin (FXN) gene on chromosome 9 (9q13-q1.1)." (PMID 32013267, 2020). "Friedreich's ataxia (FRDA) is an autosomal recessive neurodegenerative disease caused by reduced expression of the mitochondrial protein frataxin (FXN)." (PMID 32586831, 2020). "Friedreich’s ataxia (FRDA) is a neurodegenerative disease caused by recessive mutations in the frataxin gene that lead to a deficiency of the mitochondrial frataxin (FXN) protein." (PMID 33158039, 2020). "Frataxin overexpression in the nervous system reduces lifespan, impairs locomotor ability and causes brain degeneration." (PMID 29794127, 2018). "This idea is supported by studies showing that some neurodegenerative disease models, such as reduced frataxin expression or PINK1 mutation, show reduction of both mitochondrial transport and membrane potential." (PMID 28542430, 2017). "Friedreich’s ataxia (FRDA) is a severe neurodegenerative disease caused by GAA repeat expansion within the first intron of the frataxin gene." (PMID 23382970, 2013). "Oxidative stress has been implicated in the pathogenesis of Friedreich’s Ataxia (FRDA), a neurodegenerative disease caused by the decreased expression of frataxin, a mitochondrial protein responsible of iron homeostasis." (PMID 23574943, 2013). "(FA) is an autosomal recessive neurodegenerative disease caused by a homozygous GAA trinucleotide repeat expansion in the first intron of the FXN gene, encoding for the mitochondrial FXN protein." (PMID 32369911, 2020). "Overall, the evidence strongly identifies FA as a metal-induced neurodegenerative disease and suggest a role for frataxin in maintaining the correct threshold against ferroptosis." (PMID 33202971, 2020). "Decreased expression of mitochondrial frataxin (FXN) causes Friedreich’s ataxia (FRDA), a neurodegenerative disease with type 2 diabetes (T2D) as severe comorbidity." (PMID 31974344, 2020). "The interest for frataxin, a protein previously totally ignored, was originally raised in 1996 when the protein was linked to FRDA, a rare but lethal neurodegenerative disease." (PMID 30636112, 2019).
neurodegenerative disease (continued). "FRDA is a rare genetic neurodegenerative disease that involves the partial silencing of frataxin, a small mitochondrial protein that was completely overlooked before being linked to FRDA." (PMID 29197070, 2018). "Another striking example linking the iron-metabolism to neurodegenerative disease is the protein frataxin, which itself is the iron-importer into mitochondria." (PMID 26335097, 2015). "A comprehensive transcriptome analysis in Friedreich’s ataxia (FRDA) patients, a hereditary neurodegenerative disease characterized by guanine-adenine-adenine (GAA) nucleotide repeat expansion in the first intron of the frataxin (FXN) gene, identified BDNF and FXN as novel targets of miRNAs." (PMID 35743271, 2022). "The neurodegenerative disease Friedreich’s ataxia (FRDA; OMIM 229300) results from low FXN expression, primarily caused by an abnormal GAA triplet repeat expansion in the first intron of the frataxin gene." (PMID 34944579, 2021). "Friedreich’s ataxia (FA) is a neurodegenerative disease with no approved therapy that is the result of frataxin deficiency." (PMID 31665133, 2019).
cancer (20 papers, 2009 to 2025). A tumor composed of atypical neoplastic, often pleomorphic cells that invade other tissues. "This work studies the stability of wild-type frataxin and some of its variants found in cancer tissues upon Co2+ binding." (PMID 35712353, 2022). "In cancer cells, FXN overexpression is associated with hypoxia-induced tumor stress via the HIF pathway." (PMID 36338346, 2022). "The expression of FXN is increased in a variety of tumor cell lines in response to hypoxic stress, which is often associated with the progression of cancer." (PMID 36338346, 2022). "However, it has been reported by Pastore and Puccio (2013) that, in cancer tissues, several FXN variants, whose stability and functional activity are reduced with respect to the wild-type (wt), are present." (PMID 35712353, 2022). "More recent information concerning FXN is the role of variants in cancer." (PMID 35335316, 2022). "FXN has been demonstrated to be a key regulator of ferroptosis through regulating iron homeostasis and mitochondrial function in several cancers." (PMID 40564039, 2025). "In contrast, frataxin, another protein involved in Fe-S clusters assembly, is upregulated in different cancer types and promotes cancer cell resistance to ferroptosis." (PMID 38095762, 2024). "Due to its well-known role in Friedreich’s Ataxia (FA), FXN has been a point of interest in cancer research." (PMID 34573089, 2021). "Noteworthy, in cancer cells, the frataxin knockdown reduces the growth of xenograft tumors in nude mice." (PMID 33202971, 2020). "Modulation of both mitochondrial FXN and NEET proteins has been associated with CDI ferroptosis in cancer cells." (PMID 32575749, 2020). "The expression levels of ferrochelatase and frataxin, which transports mitochondrial labile iron ion to ferrochelatase, were also lower in cancer specimens." (PMID 25822972, 2015). "The anti-cancer compounds cisplatin (3.3 μM) and camptothecin (20 nM) were found to increase the level of FXN mRNA by over 2-fold in FRDA lymphoblasts." (PMID 23418481, 2013). "Compounds that were established to increase FXN gene expression and frataxin levels included several anti-cancer agents, the iron-chelator deferiprone and the phytoalexin resveratrol." (PMID 23418481, 2013). "As for cancers, knockdown of FXN could activate the iron starvation response and make breast cancer cells more sensitive to ferroptosis." (PMID 40564039, 2025). "Taken together, FXN may be thought about as an antioxidant and potential tumor-suppressor but its role in the various stages of cancer development remain unclear." (PMID 34573089, 2021). "Despite the role of frataxin in cancer is unknown, the relation between FA and malignancy has been suggested." (PMID 23844591, 2013). "We subsequently investigated the correlations between the CNV of ISCA1 and the RNA expression of FRGs and reported that the ISCA1 CNV was positively correlated with TSC1, FXN, BRD3, and MAPKAP1 in most cancer types." (PMID 39766805, 2024). "GRP75 physically interacts with frataxin in human embryonic kidney 293 (HEK293) and COS7 cells, and knockdown of GRP75 decreases the level of frataxin in cancer cell lines." (PMID 38920668, 2024). "Frataxin (FXN) and NFS1 cysteine desulfurase are both required for ISC synthesis and are overexpressed in cancer cells." (PMID 37190037, 2023). "Suppression of FXN impairs mitochondrial morphology, prevents Fe–S cluster assembly and enhances CDI ferroptosis in HT-1080 cancer cells." (PMID 32575749, 2020).
genetic disorder (15 papers, 2014 to 2025). "Friedreich’s ataxia (FRDA) is a recessive genetic disorder involving mainly the nervous system, caused by mutations in the gene frataxin (FXN), which is located in the centromeric region of chromosome 9q." (PMID 35682973, 2022). "FRDA is a rare genetic disorder caused by an insufficient quantity of frataxin protein." (PMID 31584077, 2019). "Expansion of the trinucleotide GAA within an intronic FXN RNA can cause Friedreich's Ataxia (FRDA), an incurable genetic disorder." (PMID 26842135, 2016). "In addition, FRDA is a genetic disorder, and frataxin expression in different tissues does not explain this selective vulnerability." (PMID 26785073, 2014).
neurological disorder (15 papers, 2011 to 2025). "For example, expansions in replication factor C subunit 1 (RFC1) and frataxin (FXN) are also associated with neurologic disorders." (PMID 41278766, 2025). "Friedreich’s Ataxia (FRDA) is a progressive neurological disorder caused by mutations in both alleles of the frataxin (FXN) gene." (PMID 35368287, 2022). "Friedreich's ataxia (FRDA) is a devastating neurological disorder caused by a GAA trinucleotide repeat expansion within intron 1 of the frataxin (FXN) gene (Pandolfo 2009; Bürk 2017)." (PMID 31151992, 2019). "To investigate the possibility to modulate the FTMT epigenetic control in pathological models, we chose FRDA, a neurological disorder caused by the deficiency of frataxin (FXN), a mitochondrial iron-chaperon involved in iron sulfur cluster biosynthesis." (PMID 27625068, 2016). "Friedreich’s Ataxia (FRDA) is a rare neurological disorder caused by an abnormal expansion of Guanine-Adenine-Adenine (GAA) repeat in intron 1 of the FXN gene, which encodes frataxin, leading to reduced expression of frataxin, a mitochondrial protein essential for cellular homeostasis." (PMID 40375363, 2025). "The highly selective A-196 SUV4-20H inhibitor has been shown to increase FXN expression in FRDA patient-derived cells, supporting the relevance of SUV4-20H inhibition for the treatment of neurological disorders associated with increased SUV4-20H expression or activity." (PMID 35563127, 2022). "The correlation between reduced frataxin levels (longer GAA expansions) and earlier onset neurological disease implies a role for frataxin in maintenance and protection of neurons." (PMID 22016819, 2011). "Furthermore, a correlation between reduced frataxin levels (longer GAA expansions) and earlier-onset neurological disease implies a role for frataxin in maintenance and protection of neurons." (PMID 28456899, 2017).